AFP (alpha fetoprotein)
Diseases named in the same sentence as AFP in open-access papers (continued):
Sharing a sentence is not in itself a finding about the gene and the disease.
liver cirrhosis (continued). "Random forest (RF) analysis was further used to discriminate AFP negative HCC patient from liver cirrhosis patients based on 15-metabolites panel, which showed relatively low error rate of 25.49% in the training set." (PMID 36845695, 2023). "The three-marker model is accurate to distinguish AFP negative HCC patients from liver cirrhosis patients." (PMID 36845695, 2023). "The results showed that the AUC of AFP and EV-DLEU2 in mUICC stage I HCC were 0.508 and 0.885, respectively, compared with those in NL, CH, and liver cirrhosis, indicating that EV-DLEU2 performed significantly better than AFP in the detection of HCC at the very early stage." (PMID 37095423, 2023). "The study discovered that exosomal miR-48a performed significantly better than AFP in distinguishing HCC from liver cirrhosis (with an AUC of 0.891 compared to 0.712) but failed to discriminate HCC from chronic hepatitis." (PMID 37765333, 2023). "At present, society guidelines recommend HCC primary surveillance for liver cirrhosis, or at-risk patients with chronic hepatitis B (CHB), based on abdominal ultrasound (US) evaluation with or without serum alpha-fetoprotein (AFP) levels." (PMID 37627125, 2023). "Whereas, UBE2MP1 transcription shows an adverse relationship with the tumor size (P<0.05), serum Alpha-fetoprotein (AFP) quantity (P<0.05), more advanced TNM stages (P<0.05), tumor microsatellite formation (P<0.05), invasion of venous (P<0.05), and liver cirrhosis stages (P<0.05)." (PMID 36214767, 2022). "The average age, sex ratio, preoperative tumor marker AFP, tumor size, presence or absence of liver cirrhosis, and other basic information of patients in each group were recorded and compared." (PMID 35634437, 2022). "Age, male sex, AFP level, liver cirrhosis, tumor size, and time to recurrence were not identified as risk factors (P>0.05)." (PMID 36713526, 2022). "However, significant difference was noted between patients with HCC and patients with liver cirrhosis regarding serum insulin, presence of insulin resistance and liver function ALT, AST, GGT, AFP, serum albumin, GLR, TAG/HDL-C, and LAIR-1 expression." (PMID 36293412, 2022). "Therefore, in the clinical setting of a patient with liver cirrhosis and PVT, AFP levels higher than 20 ng/dL can be highly suggestive of the presence of TIV." (PMID 35626300, 2022). "Whether Golgi protein 73 alone is superior to AFP in detecting HCC and discrimination from liver cirrhosis is controversial." (PMID 36518320, 2022). "Lastly, we performed a second PSM to match the viremic HCC with subsequent SVR and the post-SVR HCC patients by liver cirrhosis, impaired liver status, AST, ALT, creatinine, AFP, BCLC stage 0/A, curative therapy, and HCC diagnosis year yielding 80 pairs of patients with comparable characteristics." (PMID 34298669, 2021). "Patients with intrahepatic cholangiocarcinoma are usually negative for chronic hepatitis, liver cirrhosis, and alpha-fetoprotein." (PMID 34772340, 2021). "Unfortunately, AFP does not have sufficient sensitivity and specificity to differentiate between liver cirrhosis and early HCC." (PMID 34436504, 2021). "However, to date, screening of patients with liver cirrhosis for HCC mostly relies on suboptimal ultrasound-mediated evaluation and α-fetoprotein (AFP) measurement." (PMID 34362181, 2021). "The high circCRIM1 expression group was associated with tumor size (p = 0.0049), TNM stage (p = 0.0216), as well as Edmondson grade (p = 0.0280), rather than gender, age, liver cirrhosis, AFP, or HBsAg (p > 0.05)." (PMID 34869393, 2021). "The PSM (on liver cirrhosis, impaired liver status, AST, ALT, creatinine, AFP, BCLC stage 0/A, and curative therapy) to compare post-SVR and viremic HCC patients yielded 140 pairs of post-SVR HCC and viremic HCC patients who were comparable in most characteristics." (PMID 34298669, 2021).
liver cirrhosis (continued). "Meanwhile, miR-10b-5p+miR-221-3p+miR-223-3p shows better efficacy in distinguishing low AFP-HCC from non-HCC hepatitis or liver cirrhosis patients compared to the combination of the four miRNAs (AUC = 0.84)." (PMID 33869059, 2021). "Multivariate analysis revealed that diabetes mellitus (DM) (p = 0.011), alpha-fetoprotein levels (AFP) (p < 0.001), low platelet count (p = 0.008), liver cirrhosis (p < 0.001), and the first year of ALBI grade after resection (p < 0.001) were independent predictors for RFS." (PMID 32350365, 2020). "Significantly increased serum AFP values (>15 ng/ml) can be found in 30.1% of patients with compensated liver cirrhosis due to HCV infection without HCC." (PMID 32341704, 2020). "In addition to BMP1 (0.8, cancer/liver cirrhosis, p = 0.013), Trim22 was less abundant in HCC patients with normal AFP than liver cirrhosis patients, and this difference was statistically significant (0.6, cancer/liver cirrhosis, p < 0.001)." (PMID 31979338, 2020). "The median level of serum AFP showed significantly higher values in HCC group than in liver cirrhosis and HCV groups, (p <0.001 and <0.001 respectively), and also showed significantly higher values in the liver cirrhosis group than in the HCV group (p <0.001)." (PMID 32102538, 2020). "High serum uPA was associated with hypoalbuminemia (p < 0.001), thrombocytopenia (p = 0.032), and liver cirrhosis (p < 0.001), but not with other characteristics such as gender, age, etiology, AFP, tumor size, vascular invasion, and pathological stage." (PMID 31791275, 2019). "However, the specificity of AFP for HCC diagnoses is relatively low, as it is sometimes increased in patients with chronic liver diseases, such as chronic hepatitis and liver cirrhosis." (PMID 31451706, 2019). "In univariate analysis, ALT elevation (grade ≥1) was significantly or marginally associated with the following factors: female gender (p = 0.074), liver cirrhosis (p = 0.043), rs4646437 genotype CC (p = 0.045), AST ≥46 IU/L (p = 0.070), and alpha-fetoprotein ≥5.9 ng/mL (p = 0.088)." (PMID 31291311, 2019). "All patients with compensated liver cirrhosis will undergo noncontrast US or MRI, with serum AFP testing every 6 months." (PMID 30249190, 2018). "Furthermore, high HOXC6 expression, high AFP level, high GGT level, liver cirrhosis, larger tumor, tumor number, satellite nodule and vascular invasion were unfavorable predictors for TTR of HCC patients (all P < 0.05)." (PMID 29348394, 2018). "In addition, it was detected that high miR-1247-3p expression was correlated with increased alpha-fetoprotein (AFP) level, liver cirrhosis, tumor thrombus, and distant metastasis." (PMID 29335551, 2018). "Comparison of HCC patients with liver cirrhosis cases with no diagnosis of HCC revealed significantly high AFP (p < 0.001) and IL-6 levels (p < 0.001) in HCC group." (PMID 29963457, 2018). "Furthermore, recurrence‐free survival rates tended to be more favorable in patients with albumin <4.0 g/dL, microscopic vascular invasion, tumor size >2.0 cm, AFP >20 ng/dL, ALT >30 IU/L, T‐Bil >1.0 mg/dL, and liver cirrhosis." (PMID 30003195, 2018). "Comparison of HCC patients with liver cirrhosis cases with no diagnosis of HCC (n = 55) revealed significantly high AFP (p < 0.001) and IL-6 levels (p < 0.001) in the HCC group." (PMID 29963457, 2018). "Alpha-fetoprotein (AFP) has been the most widely used serum biomarker for HCC diagnosis, but the elevated serum AFP levels (>7 ng/ml) are also frequently observed in some patients with benign liver diseases (BLD), such as liver cirrhosis (LC) and chronic hepatitis (CH)." (PMID 29228649, 2017). "The AUC value of DCP + AFP was no significantly higher than that in DCP or AFP (0.860 vs. 0.805 vs. 0.859) for distinguishing HCC from liver cirrhosis." (PMID 29163838, 2017).
liver cirrhosis (continued). "Patients with strong PDGFRα expression on HCC showed similar gender ratio, higher proportion of patients with AFP >200 ng/mL, and lower portion of patients with liver cirrhosis compared with patients with either no or moderate PDGRα stain." (PMID 28465473, 2017). "Further investigations revealed the prognostic value of CCL24 expression in HCCs with AFP > 20 ng/mL, without liver cirrhosis, within a solitary tumor, microvascular invasion, and TNM stage II+III in the HCC patient subgroups." (PMID 28042950, 2017). "Other characteristics, including sex, HBsAg, AFP, liver cirrhosis, tumor number, and tumor encapsulation, were not related to CD109 expression on tumor vessels." (PMID 27121053, 2016). "The remarkable findings of the 15 HCC patients shown by this study include a high rate of the presence of liver cirrhosis, a poor prognosis, a promising role of follow‐up in improving the prognosis of HCC, and the usefulness of using AFP levels in the diagnosis of HCC during the follow‐up." (PMID 27748053, 2016). "The results revealed that low expression of Cezanne (P < 0.001), high AFP level (P = 0.016), high GGT level (P = 0.001), liver cirrhosis (P = 0.006), larger tumor size (P < 0.001) and vascular invasion (P < 0.001) were unfavourable predictors for OS of HCC patients." (PMID 25638165, 2015). "There were no between-group differences in liver cirrhosis, etiology, Child–Pugh score, ascites, extrahepatic tumor metastasis or portal vein invasion, or serum alpha-fetoprotein levels." (PMID 25689846, 2015). "Other clinical characteristics, including age, sex, preoperative serum alpha-fetoprotein, γ-GT, liver cirrhosis, tumor encapsulation, and TNM stage, were not directly related to the expression of PKM2." (PMID 25514599, 2015). "This means that the well-known nonspecific elevations of AFP in patients with liver cirrhosis were not significantly elicited with serum MDK increasing its specificity as a novel diagnostic marker for HCC." (PMID 25737783, 2015). "Other parameters including age, gender, ECOG performance status, pretreatment CP class, pretreatment AFP level, presence of hepatitis or liver cirrhosis, previous treatments, and treatment after RT did not influence the possibility of RIHT." (PMID 26512611, 2015). "The results showed that high expression of Cripto-1 (P < 0.001), high AFP level (P < 0.001), high GGT level (P = 0.009), liver cirrhosis (P = 0.006), larger tumor size (P < 0.001) and vascular invasion (P < 0.001) were unfavourable predictors for OS of HCC patients." (PMID 26375669, 2015). "Some studies have suggested using a serum AFP level of >400 ng/mL to diagnose HCC, or a solid mass >2 cm in diameter with typical features of HCC on at least one imaging study in a patient with liver cirrhosis." (PMID 24993566, 2014). "Consequently, the discriminatory power was examined for total AFP and glycosylated AFP in serum samples from normal healthy controls versus HCC patients and liver cirrhosis versus early-stage HCC patients." (PMID 25310463, 2014). "Clinicopathologic characteristics, including size of tumor, vascular invasion, tumor number, capsular formation, AFP level, liver cirrhosis, and Child-Pugh classification, showed no statistical difference between two groups." (PMID 24894964, 2014). "Consequently, on measuring AFP concentrations in serum from HCC patients versus normal healthy controls and early-stage HCC versus liver cirrhosis by MRM-MS, AFP deglycopeptides had greater power in distinguishing, compared with nonglycopeptides." (PMID 25310463, 2014). "Multivariate analyses showed that gamma-glutamyltranspeptidase and baseline AFP were predictors of PFS (all P < 0.05) and that male gender, the presence of liver cirrhosis, baseline DCP, number of measurable tumors and AFP response were independent predictors of OS (all P < 0.05)." (PMID 23282286, 2013).
liver cirrhosis (continued). "Age, gender, pretreatment level of AFP, and the presence of hepatitis and/or liver cirrhosis did not contribute to an increase in CP score after helical tomotherapy." (PMID 23298438, 2013). "Our patient had an elevated serum AFP level and a gastric cancer with liver metastasis without viral hepatitis or liver cirrhosis; however, the immunohistochemical analysis showed that the tumor was AFP-negative." (PMID 22018031, 2011). "Thus, this analysis aimed to evaluate the cost-effectiveness of routine HCC surveillance using GALAD, GAAD, and PIVKA-II plus AFP (PIVKA-II + AFP) compared to US + AFP or no routine surveillance amongst Thai patients with compensated liver cirrhosis (CLC)." (PMID 41490253, 2026). "Therefore, most studies have focused on distinguishing AFP-negative HCC from benign liver diseases (liver cirrhosis (LC), chronic hepatitis and so on) and normal groups with no significant increase in AFP." (PMID 35002508, 2022). "Furthermore, we also found when the patients with different status, such as AFP (<400 ng/mL), Liver cirrhosis (Negative), Tumor thrombus (Negative), Tumor numbers (Single) and TACE (Post-operation), high-frequency mutations was associated with poor prognosis." (PMID 35921289, 2022). "Indeed, AFP cannot distinguish between small HCC masses and liver cirrhosis." (PMID 36363693, 2022). "We also found that high-frequency mutation was associated with poor prognosis though patients had better pathological characteristics, such as AFP (<400 ng/mL), Liver cirrhosis (Negative), Tumor thrombus (Negative), Tumor numbers (Single) and Post-operation TACE (Executed)." (PMID 35921289, 2022). "Additionally, evaluation of serum AFP level and albumin-bilirubin (ALBI) grade, along with liver cirrhosis, tumor margin, and radiomics signatures have increased ML-based contrast-enhanced CT performance accuracy in the prediction of HCC recurrence rate after curative tumor resection." (PMID 33562077, 2021). "However, it was not related to age, gender, liver cirrhosis, HBsAg status, AFP, tumor multiplicity, and Edmondson grade." (PMID 34721576, 2021). "However, it was not related to age, gender, liver cirrhosis, HBsAg status, AFP, tumor multiplicity or Edmondson grade." (PMID 34666613, 2021). "Results of the univariate analysis indicated that the following factors did not predict both OS and DFS: age, sex, hepatitis B virus, liver cirrhosis, alpha-fetoprotein concentration, alanine aminotransferase concentration, tumor number, and tumor encapsulation." (PMID 34081621, 2021). "Higher levels of AFP (over 15 ng/ml) in patients with compensated liver cirrhosis without HCC were significantly correlated with advanced age, severe necroinflammatory activity detected by FibroMax, severe NASH, severe steatosis, low platelets and increased values of AST and ALT." (PMID 32341704, 2020). "Moreover, overexpression of AFP levels can also be observed in some patients with the non-malignant chronic liver disease, including 15–58% with chronic hepatitis and 11–47% with liver cirrhosis." (PMID 31205886, 2019). "However, TIPE2 mRNA was not significantly related to age, sex, HBeAg, liver cirrhosis, multiple primary tumor number and serum AFP level." (PMID 31661000, 2019). "However, differences by age, gender, AFP content, or tumor size, liver cirrhosis and differentiation in serum miR‐130b levels were all not statistically significant (p > .05)." (PMID 31660696, 2019). "Second, AFP levels in patients with HBV infection could be affected by non-malignancy-related factors such as liver cirrhosis, acute hepatitis, and chronic liver disease." (PMID 29930697, 2018). "In addition, low CLCA4 expression (P < 0.001), high AFP level (P = 0.004), high GGT level (P = 0.010), liver cirrhosis (P = 0.019), larger tumor (P < 0.001), satellite nodule (P = 0.002) and vascular invasion (P < 0.001) were unfavourable prognostic factors for TTR of HCC patients." (PMID 30312171, 2018).
liver cirrhosis (continued). "However, other clinical characteristics including age, sex, HBsAg background, tumor differentiation, liver cirrhosis, preoperative serum alpha-fetoprotein (AFP), and Child-Pugh scores were not significantly related to the expression of RNF187." (PMID 29254210, 2017). "However, the serum AFP level is also increased in other nonhepatoma diseases such as liver cirrhosis and acute and chronic hepatitis, which makes it difficult to diagnose primary hepatoma at an early stage using AFP alone." (PMID 27136596, 2016). "DCP not only is complementary to AFP in identifying AFP-negative HCC and in excluding AFP-positive non-HCC (liver cirrhosis), but also demonstrates improved performance in HCC surveillance, early diagnosis, treatment response and recurrence monitoring in the HBV-related population." (PMID 27070780, 2016). "The correlation analysis revealed that decreased BRD7 expression was significantly associated with TNM stage (P = 0.002) and tumor size (P = 0.008), but not with gender, age, HBsAg, serum AFP, liver cirrhosis, histological differentiation, tumor capsule or tumor number." (PMID 26919247, 2016). "In cohort A, which comprised 521 subjects, including patients with HCC, liver metastasis, liver cirrhosis (LC), and liver hemangiomas as well as healthy controls (HCs), the accuracy of DCP for distinguishing HCC from various controls was 6.2–9.7% higher than that of AFP." (PMID 27070780, 2016). "Chi-square analysis revealed that the expression of WWP1 in HCC tissues was highly correlated with tumor size (P = 0.015), histological grade (P < 0.001), TNM stage (P < 0.001), vascular invasion (P = 0.018) and tumor capsule (P = 0.026) but not with age, sex, HBV, serum AFP or liver cirrhosis." (PMID 26506518, 2015). "Moreover, AFP results were not influenced by the severity of liver cirrhosis, assessed by Child-Pugh score." (PMID 26122937, 2015). "Chi-square analyses revealed that CK2α expression was positively correlated with histological grade (P = 0.033), distant metastasis (P = 0.003) and tumor stage (TNM) (P = 0.012), but not with tumor size, liver cirrhosis, vascular invasion, serum AFP or tumor capsule." (PMID 26430962, 2015). "In the multivariate regression analysis, the association of promoters II+III with HCC metastasis was independent of age, sex, HBsAg status, liver cirrhosis, serum AFP level, Edmondson grade, tumor size, and TNM stage (for promoter II+III: 53.8% vs. 40.7%, P = 0.0004; OR = 1.70, 95% CI, 1.16–2.21)." (PMID 24603412, 2014). "Although AFP is a widely used serological marker for detection of HCC, its sensitivity and specificity are not optimal and it may also increase in patients with acute and chronic viral hepatitis, liver cirrhosis, and toxic injury." (PMID 23915185, 2013). "Moreover, many HCCs do not express AFP; on the contrary, liver cirrhosis and other intrahepatic and extrahepatic non-HCC tumors may be associated with an increase in AFP serum levels." (PMID 36230554, 2022). "The measurement of AFP in the blood, which is one of the most widely used screening tests to diagnose HCC, has a limited sensitivity and specificity given that some liver nodules may not release AFP, and patients with chronic active hepatitis or liver cirrhosis may have high levels of AFP." (PMID 29597259, 2018). "Patients with compensated liver cirrhosis at regular HCC surveillance using US and alpha-fetoprotein, with adequate renal function and without HCC diagnosis, were enrolled." (PMID 40888625, 2025). "AFP levels can be elevated not only in HCC but also in various non-malignant conditions such as chronic hepatitis B and C, liver cirrhosis, acute hepatitis, and pregnancy." (PMID 40430002, 2025). "The levels of AFP (p = 0.661), AFP-L3 (p = 0.756), and DCP (p = 0.605) as well as the GALAD score (p = 0.499) were similar between patients with and without liver cirrhosis." (PMID 38319485, 2024).